CD40 (CD40 molecule)
Diseases named in the same sentence as CD40 in open-access papers (continued):
Sharing a sentence is not in itself a finding about the gene and the disease.
tumor (continued). "CD40, part of the tumor-necrosis factor receptor family, is found on various immune and tumor cells, while its ligand (CD40L) is expressed on activated T cells, platelets, and macrophages." (PMID 40106404, 2025). "Another in vitro study revealed that NE treatment with a cocktail consisting of TNF‐α, CD40 agonist, and a tumor‐specific antibody showed increased tumor‐killing activity in human tumor cells through ADCC." (PMID 39801750, 2025). "In colorectal cancer, CD40 agonists have been shown to improve antigen presentation by tumor-resident DCs and promote T cell infiltration and expansion within the tumor microenvironment." (PMID 40821795, 2025). "IgE engagement of monocytes via the Fc region induced tumor cell cytotoxicity and a pro-inflammatory shift with upregulation of immune-stimulatory CD40, CD80 and CD86, and downregulation of scavenger CD163, cell surface molecules." (PMID 40074330, 2025). "While we noted an infiltration of T cells into tumors harboring tumor cells in a senescent-like state, DCs were depleted and showed diminished surface levels of CD40, indicating an insufficiency in signals needed to activate effector T cells." (PMID 40299790, 2025). "Reduced tumor volume and, in combination with anti-PD-L1 and CD40 agonist, improved survival with minimal toxicity." (PMID 40918451, 2025). "The unique design of OPTIMIZE-1, incorporating a tumor-priming dose of mitazalimab prior to chemotherapy, allowed us to study the correlation between CD40 stimulation and survival benefits (“Tumor-priming phase—Mita effects”)." (PMID 41061701, 2025). "The proinflammatory phenotype observed in microglia and macrophages with the upregulation of antigen presentation molecules encouraged us to study their role in the anti-tumor effect observed in the Delta-24-RGD+anti-CD40 combination." (PMID 40578365, 2025). "Same as pamidronate, but 100 times as potent.Additionally, has in vitro direct anti-tumor effects by down-regulating IL-6 secretion and reducing CD40, CD49d, CD54, and CD106 expression." (PMID 40862742, 2025). "Selecting the appropriate intracellular domain (e.g., 4‐1BB, FLT3 or CD40) of CAR can induce the mature phenotype of CAR‐DC when recognising the tumour, and overcome the acclimation of tolerant DC cells by the suppressive TME." (PMID 41292193, 2025). "Mitazalimab is another CD40 agonist studied for its role in activating APCs and enhancing the anti-tumor immune response." (PMID 40872551, 2025). "Targeting CD40 with a bsAbs can activate the CD40-dependent signaling pathways that support the recruitment and expansion of tumor-specific T-cells." (PMID 41335396, 2025). "Our research now demonstrates that CD40L on CD8+ T cells halts tumor progression by directly triggering caspase-8 activation in CD40+ cancer cells, resulting in CD40L-mediated cytotoxicity." (PMID 40397730, 2025). "In this context, activating DCs through CD40 promotes a sustained anti-tumor T cell response, as indicated by enhanced T cell proliferation." (PMID 40578365, 2025). "Anti-CD40 injection significantly elevated the number of tumor-infiltrating CD45+F4/80+ macrophages." (PMID 41176316, 2025). "Following the combination of CD40 agonist monoclonal antibody and ICIs, significant tumor regression was observed in animal models with various tumor types like PDAC, bladder cancer and cholangiocarcinoma." (PMID 40380196, 2025). "Although agonistic CD40 antibodies remain promising, therapeutic strategies aimed at enhancing their efficacy and lowering toxicity must consider the tumor-specific immune landscape to avoid unintended consequences." (PMID 40060615, 2025). "To assess the impact of lidocaine on macrophage polarization within the tumor microenvironment, we evaluated the expression of CD163 and CD40 on CD14+ tumor-infiltrating immune cells (TIICs)." (PMID 40244064, 2025).
tumor (continued). "When combined with chemotherapy, CD40 antibody agonists activate APCs to destroy tumor stroma and drive anti-tumor T cell responses in mouse models." (PMID 40430543, 2025). "CD40, a member of the tumor necrosis factor receptor family, enhances anti-tumor immunity by stimulating antigen-presenting cell activation through interactions with T cells." (PMID 40343509, 2025). "CD40 has emerged as a promising target in tumor immunotherapy and has advanced to Phase I and II clinical trials." (PMID 41141930, 2025). "Overall, this preliminary study has determined Flash-5 Gy to be the optimal dose for combining with LIFE Biomaterial loaded with anti-CD40 to generate an anti-tumor effect in prolonging the overall survival of the mice." (PMID 41155910, 2025). "This study confirms that SFV increases the expression of T-cell chemoattractant genes Cxcl9, Cxcl10, Cxcl11 and immune checkpoint molecule gene Cd40, promoting anti-tumour immunity." (PMID 40547518, 2025). "Systemic administration of an agonistic CD40 antibody (aCD40) induced T cell proliferation and activation in tumor-draining lymph nodes and attracted effector T cells to the tumor bed from the periphery." (PMID 40585246, 2025). "Specifically, CD20+ B cells and CD8+ T cells use the CD40/CD40L co-stimulatory signal to trigger T cell-mediated tumor destruction." (PMID 41285707, 2025). "As multiple cells in the tumor microenvironment express CD40, CD40L-CD28 engineers enhanced T-cell infiltration, and CD40L activates CD40-expressing immune cells to amplify anti-tumor responses." (PMID 40129944, 2025). "Two weeks after the tumor inoculation, both groups of mice were given aerosol delivery of green fluorescence-tagged polymer NPs and red fluorescence-tagged anti-CD40 for 30 min simultaneously." (PMID 40278452, 2025). "Our results with alternative formulations of rWTC-MBTA demonstrated the importance of this direct activation of the adaptive immune response through anti-CD40-mAb to curb the tumor metastasis of “cold” tumors like TNBCs." (PMID 39941108, 2025). "One week after liposomal priming, systemic administration of peptides and a costimulatory agonistic CD40 antibody enables ultrarapid expansion of T cells, resulting in massive expansion of tumor-specific T cells in the peripheral blood two weeks after priming." (PMID 39741195, 2025). "Agonistic CD40 antibody therapy has been shown to induce liver damage, primarily attributed to tumor-derived PMN-MDSCs12,30." (PMID 40060615, 2025). "CD40 activation empowers DCs to stimulate anti-tumor T cells and can reprogram macrophages to eradicate tumor stroma." (PMID 40597436, 2025). "Systemic administration of Flt3L, followed by a TLR3 agonist poly(I:C) or CD40 agonist, has been reported to successfully promote the expansion and activation of tumor-residing cDC1s and enhances tumor responses to anti-PD-L1 therapy." (PMID 41459487, 2025). "CD40 agonists have shown promise in enhancing anti-tumor immunity by activating antigen-presenting cells and bridging innate and adaptive immune responses." (PMID 40821795, 2025). "Nonetheless, the actual clinical efficacy and means of targeting CD40 for the immune subtype remains to be confirmed through further validation in tumour models." (PMID 39548315, 2025). "In Fgl2−/− mice, ovarian tumors displayed enhanced infiltration of cDC1s, CD3+ T cells, and DNAM-1+ NK cells, and they induced expression of co-stimulatory markers (MHC-II, CD86+, and CD40+) in spleen, resulting in reduced tumor burden." (PMID 41470247, 2025). "Liver- and tumor-associated markers, such as AADAC, CLRN3, GPC3, CD40, and ALB, were downregulated in LC4 cells compared to freshly isolated tumor core cells and parental tissues." (PMID 40431665, 2025). "Subsequently, the ratio of tumor-infiltrating CD8+ central/effect memory T cells vs. exhausted CD8+ T cells was significantly increased after CD40 agonist treatment, consistent with observation in the PW group." (PMID 40312419, 2025).
tumor (continued). "Current efforts emphasize engineering tumor‐targeted or conditionally active CD40 agonists or intratumoral delivery to minimize systemic exposure and enhance therapeutic indices." (PMID 40667699, 2025). "For example, a CD40-specific bispecific antibody effectively redirected Vγ9Vδ2 T cells to kill tumor cells while simultaneously blocking the pro-survival signaling of CD40, resulting in prolonged survival in mouse models of CLL." (PMID 40227601, 2025). "This robust anti-tumor effect correlated with the increase in intratumoral CD40 + DCs and the frequency of granzyme B+/IFN-γ+/TNF-α+ polyfunctional antigen-specific CD8 + T cells." (PMID 40500288, 2025). "In contrast to anti-CD40 antibodies, CD40L is specifically induced in CD8+ T cells upon tumor-specific antigen recognition, making them precise cellular CD40 agonists." (PMID 40397730, 2025). "CD40 agonists (such as Selicrelumab) promote tumor antigen presentation and T cell activation by activating CD40 receptors on the surface of dendritic cells, and form an “antigen release-presentation-response” closed loop when combined with gemcitabine." (PMID 41293424, 2025). "Coupled with mounting evidence regarding the synergy between CD40 agonists and other immunotherapies, these results advocate for further exploration of CD40-based interventions tailored to specific tumor types and unique molecular and immunologic profiles." (PMID 41182434, 2025). "CD40‒HER2 BsAb‐11 also increased tumour‐infiltrating granzyme B+ CD8+ T cells and iNOS+ macrophages." (PMID 40726342, 2025). "Tumor phagocytosis by cDC1 cells was also improved when CD40 signaling was activated, and tumor cells were previously infected with the Delta-24-RGD virus compared to single agents." (PMID 40578365, 2025). "This study shows that the intratumoral co-administration of Delta-24-RGD and a CD40 agonistic antibody is well tolerated and induces long-term anti-tumor immunity, including complete responses (up to 40%) in DMG preclinical models." (PMID 40578365, 2025). "Our group previously used a PLGA scaffold to deliver CD40-targeted mini-tLivin nanoparticles, achieving durable tumor regression in a disseminated DLBCL mouse model." (PMID 40940745, 2025). "CD40 is a type I transmembrane glycoprotein widely expressed on immune cells and tumor cells, closely related to the immune activities of T and B cells." (PMID 39457397, 2024). "Adaptive immune mediators included IL‐12, Granzyme B, CD40, PD‐L1, and IL‐17D, suggesting broad effects of alpha 1‐oleate treatment on the tumor tissues." (PMID 38553868, 2024). "Initially TNF-γ works by recruiting cohorts (CXCL9, CXCL10, CXCL11, and CXCR3) to promote antigen presentation (MHC class I and class II), T-cell initiation and activation (CD80, CD86, and CD40), and tumor cell killing (Fas and FASL)." (PMID 39835116, 2024). "Correspondingly, CD40‐positive tumours correlate with better survival in several cancer indications." (PMID 38494863, 2024). "The ADAC technology was assessed by administrating a therapeutic conjugated dose s.c. on the opposite side of tumor engraftment to minimize direct CD40-mediated anti-tumor effect e.g., mainly focusing on an abscopal effect of the vaccination setting." (PMID 39500897, 2024). "Another interesting result is that DVA enhanced the expression of CD40, which seems to produce anti-tumour effects in several tumour models." (PMID 38794272, 2024). "Multiple publications support the dependence on tumor antigen shedding and antigen presentation for optimal efficacy of CD40 agonistic antibodies." (PMID 39500897, 2024). "Recently, anti-CD40 agonist antibodies have been used in a variety of preclinical and clinical settings to induce augmented anti-tumor efficacy in a variety of regimens and combinations." (PMID 38731089, 2024).
tumor (continued). "The therapeutic triggering of canonical CD40 signaling is particularly attractive, since it provides an opportunity to elicit novel patient- and tumor-specific immune responses using a conventional biological, e.g., an agonistic antibody." (PMID 38651411, 2024). "When it comes to the tumor microenvironment, A. vulgaris extract significantly increased the percentage of CD40+ dendritic cells." (PMID 38543072, 2024). "In early studies, FGK-45, an agonistic anti-murine-CD40 antibody, was shown to stimulate cytotoxic T-cell responses and to provide protection against tumor re-challenge." (PMID 38651411, 2024). "In mice, CD40 agonism can mediate tumor clearance via stromal remodeling, induction of tumoricidal macrophages, and activation of CD4+ and CD8+ T cells." (PMID 38181044, 2024). "In a small percentage of malignancies, direct cytotoxicity from CD40 ligation on tumor cells creates a “vaccine effect” in which tumor antigens are released and subsequently acquired and cross-presented by intratumoral APCs." (PMID 38903502, 2024). "For conventional cell therapy, the antitumor efficacy of a combination of tumor-targeted antimesothelin CAR-T cells and M2 inhibitors has been confirmed and TAM-associated cell therapy based on specific markers, such as CD40, is being studied." (PMID 39003350, 2024). "To evaluate the effectiveness of NanoBE engagement, we first conducted the separated studies on the specific binding of Nano/CLDN18.2 with tumor cells and the macrophage activation induced by Nano/CD40, respectively." (PMID 38468289, 2024). "It was proved that different levels of CD40 expression on DCs have the potential to suppress anti-tumor T-cell response." (PMID 39061246, 2024). "CD40 is required for myeloid activation, and is therefore needed for myeloid-mediated tumor control." (PMID 39065651, 2024). "The toxicity and efficacy profile of the BiA9*2_HF was stress tested by benchmarking against the clinically evaluated anti-CD40 agonistic antibody selicrelumab in the TC-1 tumor model." (PMID 39500897, 2024). "Approaches involving CD40 agonists with gemcitabine to activate macrophages in the tumor or reprogramming stellate cells to reduce extracellular matrix and tumor growth, are also being developed." (PMID 38474109, 2024). "Concomitantly, HLA augmented the expression of other M1-associated markers including CD40 and CD86, which further supports that HLA shifted macrophages to anti-tumor phenotypes." (PMID 38191648, 2024). "Twelve days after s.c. implantation of 4662 MD7 cells, tumor-bearing animals were treated with either αEP4 or αPD-1 plus agonistic CD40 (aCD40), or the combination." (PMID 39298269, 2024). "In a phase II trial of metastatic melanoma patients who had progressed on checkpoint blockade, the combination of sotigalimumab (APX005M CD40 agonist antibody) and nivolumab was able to induce long-lasting clinical tumor response in a subset of patients." (PMID 38903502, 2024). "Administration of CD40 mAb has been demonstrated to induce macrophage-dependent tumor regression in mice." (PMID 39146202, 2024). "The essential role of CD40L in the induction of protective tumor immunity led researchers to expect that agonistic anti-CD40 antibodies would act as potent adjuvants to promote tumor immunity." (PMID 38461238, 2024). "CD40 monoclonal antibodies can also exert an effect through a T cell independent, macrophage-dependent anti-tumor mechanism." (PMID 38533720, 2024). "While it is undeniable that CD40/CD40L plays a crucial role in initiating anti-tumor immune responses, the full potential of this signaling pathway has yet to be fully realized by the agonists currently in clinical development." (PMID 39120299, 2024). "Flt3L plus agonistic anti-CD40 also increased DC numbers and slowed tumor growth, but to a lesser extent." (PMID 39178856, 2024).
tumor (continued). "As a result, the tumor-killing function of TAMs can be activated using agonistic anti-CD40 antibodies, thereby restoring their immunosurveillance against tumors." (PMID 39403370, 2024). "Cancers derived from CD40‐positive cells initially express CD40, but it is commonly lost as the tumour progresses." (PMID 38494863, 2024). "The anti-tumor efficacy with anti-CD40 agonists in these early-phase, dose-escalating monotherapy studies were modest, ranging from objective response rates (ORR) of 0-10% and stable response rates of 10-40%." (PMID 38153346, 2024). "Some human NBLs express CD40, and in vitro treatment with a CD40 agonist can induce tumor cell apoptosis." (PMID 38731089, 2024). "GITR’s role within HCC immune TME has also been studied regarding its correlation with CD40 expression, which is considered a marker of tumor growth." (PMID 39061246, 2024). "The CD40-CD40L axis is a key regulator of the adaptive immune response, and agonistic anti-CD40 antibodies have confirmed anti-tumor activity in preclinical models, paving the way for clinical evaluation." (PMID 39500897, 2024). "The tumor cells from the rapamycin-treated mice expressed higher levels of CD40, CD80, and ICAM-1 than those from the control mice." (PMID 38791040, 2024). "In mouse models, we show that Co-STARs mediate more robust T-cell expansion and more durable tumor regressions than TCRs similarly modified with MyD88 and CD40 co-stimulation." (PMID 38985855, 2024). "The use of combined therapies, such as CD40 agonists, tumor necrosis factor and tumor-binding antibodies drives the neutrophil-mediated eradication of cancer." (PMID 39555061, 2024). "CD40 agonists can activate T cell immunity, activate macrophages and DCs, and destroy the PC tumor matrix." (PMID 39872846, 2024). "The CD40 agonist monoclonal antibody CP-870,893 has also shown promising results across various tumor clinical trials." (PMID 39575419, 2024). "CD40 increase halts tumor growth via immune responses (T or NK-cell mediated), apoptosis, and antibody-dependent cellular cytotoxicity (ADCC)." (PMID 38890285, 2024). "The ADAC technology allows potent CD40-induced immune modulation by flexible peptide cargo delivery to skew the lymph node and tumor microenvironment toward a potent Th1 response." (PMID 39500897, 2024). "Stimulation of the CD40/CD40L axis destroys tumor cells by stimulating CD8 T lymphocytes with TNF-α; conversely, it suppresses immunity by stimulating TNF-β production and causing a tumorigenic effect." (PMID 39625893, 2024). "Total CD40 tumour expression correlated positively to improved survival, highlighting a significant role in anti-tumour immunity." (PMID 38440738, 2024). "At low levels of CD40 expression, tumor growth is promoted, while higher levels induce tumor-regressing T-cell responses." (PMID 39061246, 2024). "CD40, a member of the tumor necrosis factor receptor superfamily, is primarily expressed in leukocytes and some tumor cells." (PMID 38495490, 2024). "The use of CD40 agonist and Fms-related tyrosine kinase 3 ligand (Flt3L) enabled tumor growth control by increasing the number and activity of cDCs." (PMID 38817612, 2024). "In particular, the stimulatory receptor CD40 plays a central role in promoting antitumor immunity and developing tumor-specific T-cell responses." (PMID 38883779, 2024). "Towards this direction, they investigated the role of GITR in the context of CD40 expression levels on DCs and their influence on tumor growth or regression." (PMID 39061246, 2024). "The co-administration of a CD40 agonist and anti-PD-1/anti-PD-L1 inhibitors elevates PD-L1 expression in tumor-infiltrating monocytes and TAMs, biases the TAM populations toward the inflammatory M1 phenotype, thereby inhibiting tumor-induced immune resistance." (PMID 38341519, 2024). "By accomplishing enhanced antigen presentation and pro-inflammatory T cell support, CD40 activation potentiates anti-tumour immunity." (PMID 38440738, 2024).